SMYD2 (SET and MYND domain containing 2)
Description:
Specifically trimethylates histone H3 'Lys-4' (H3K4me3) in vivo. The activity requires interaction with HSP90alpha. Monomethylates RB1 at 'Lys-860'.
Synonyms: KMT3C; HSKM-B; ZMYND14
Tractability: Small molecule: a structure with a bound ligand is known; a high-quality ligand is known; it has a high-quality binding pocket. PROTAC: ubiquitination databases record sites on it; a small molecule that binds it is known.
Target class: Writer; Protein methyltransferase; SET domain; Epigenetic regulator
Chemical probes: BAY-598 (high quality), LLY-507 (high quality), PFI-5 (high quality)
Gene: Protein-coding gene on chromosome 1 (214,280,935 to 214,337,137, forward strand). Ensembl gene ENSG00000143499.
Subcellular location: Cytoplasm, cytosol; Nucleus
Subcellular location (Human Protein Atlas): Cytosol; Mitochondria
Pathways (Reactome):
Chromatin organization: PKMTs methylate histone lysines
Gene Ontology:
Molecular function: protein binding; protein-lysine N-methyltransferase activity; histone H3 methyltransferase activity; histone H3K36 methyltransferase activity; lysine N-methyltransferase activity; RNA polymerase II complex binding; histone H3K4 trimethyltransferase activity; histone methyltransferase activity
Biological process: negative regulation of transcription by RNA polymerase II; peptidyl-lysine monomethylation; heart development; negative regulation of cell population proliferation; negative regulation of DNA-templated transcription; peptidyl-lysine dimethylation; chromatin remodeling
Cellular component: cytoplasm; cytosol; nucleoplasm; nucleus
Genetic constraint (gnomAD): Loss-of-function variants: 46 observed, 53.64 expected, observed/expected ratio (o/e) 0.86, 90% interval 0.68 to 1.1. The upper end of that interval is the gene's LOEUF score, 1.1, which puts it in group 4 of 6, group 1 being the genes least tolerant of losing a copy. Missense variants: 486 observed, 518.21 expected, observed/expected ratio (o/e) 0.94, 90% interval 0.87 to 1.01. Synonymous variants: 203 observed, 188.12 expected, observed/expected ratio (o/e) 1.08, 90% interval 0.96 to 1.21.
Homologues: Orthologues: macaque SMYD2 (99% identical), chimpanzee SMYD2 (99% identical), dog SMYD2 (97% identical), pig SMYD2 (97% identical), mouse Smyd2 (93% identical), guinea pig SMYD2 (93% identical), rat Smyd2 (93% identical), rabbit SMYD2 (81% identical), tropical clawed frog SMYD2 (80% identical), zebrafish smyd2a (76% identical), Drosophila melanogaster Smyd3 (25% identical), Drosophila melanogaster CG18213 (23% identical), and 7 more. Paralogues in human: SMYD1 (32% identical), SMYD3 (32% identical), SMYD4 (24% identical), SMYD5 (20% identical), ZMYND15 (18% identical).
Diseases named in the same sentence as SMYD2 in open-access papers:
SMYD2 is named in the same sentence as 120 diseases in open-access papers, as found by Europe PMC text mining. Sharing a sentence is not in itself a finding about the gene and the disease. The quoted sentences say what the papers report.
breast carcinoma (35 papers, 2008 to 2025). "SMYD2 mRNA expression level is associated with metastatic relapse in the relapse-free survival of breast cancer patients, indicating that SMYD2 acts as a potential biomarker and prognostic indicator for this cancer." (PMID 36520265, 2022). "Overexpression of SMYD2 is associated with poor prognosis for patients with cancer, such as gastric, bladder, colon, and breast cancers (BCs), along with esophageal squamous-cell carcinoma, hepatocellular carcinoma, and acute lymphoblastic leukemia." (PMID 33935284, 2021). "Similar to our expression profile, high levels of SMYD2 expression has been associated with unfavorable prognosis in different cancer types, such as breast cancer (mRNA expression) and cervical cancer (protein expression)." (PMID 32133296, 2020). "However, our work demonstrates that loss of SMYD2 abrogates metastatic dissemination in mouse models of mammary tumorigenesis and human breast cancer models." (PMID 38296970, 2024). "In addition, we have identified a novel SMYD2 transcriptional target gene, PTPN13, which links SMYD2 to other known breast cancer associated signaling pathways, including ERK, mTOR, and Akt signaling via PTPN13 mediated phosphorylation." (PMID 29487338, 2018). "Our pan-cancer analysis of TCGA data revealed consistent and significant SMYD2 upregulation across multiple malignancies including GC, breast cancer, colorectal adenocarcinoma, renal cell carcinoma, and prostate cancer, validating and extending prior reports." (PMID 40777131, 2025). "Remarkably, genetic or pharmacological inhibition of SMYD2 abrogates the motility and metastatic spread of breast cancer cell lines and prevents metastatic dissemination in vivo in autochthonous mammary cancer models and patient-derived xenografts." (PMID 38296970, 2024). "In breast cancer, SMYD2-induced methylation has a suppressive effect on PTEN tumor suppressor function, resulting in the activation of the phosphatidylinositol 3-kinase-AKT pathway." (PMID 39440063, 2024). "Remarkably, SMYD2 pharmacologic inhibition efficiently impairs the metastatic spread of breast cancer cells, PDX and aggressive mammary tumors from genetically engineered mice." (PMID 38296970, 2024). "Mechanistically, we identify BCAR3 as a genuine physiological substrate of SMYD2 in breast cancer cells." (PMID 38296970, 2024). "To model metastatic colonization of the lung, we intravenously inoculated highly lung-metastatic prone MDA-MB-231 breast cancer cells with depletion of endogenous SMYD2 and/or BCAR3 complemented with WT or methyl-mutant K334A BCAR3." (PMID 38296970, 2024). "To attest the pre-clinical value of targeting the SMYD2-BCAR3 pathway to prevent breast cancer dissemination, we performed in vivo metastasis experiment with the selective SMYD2 catalytic inhibitor BAY-59835." (PMID 38296970, 2024). "Here, we identify the lysine methyltransferase SMYD2 as a clinically actionable master regulator of breast cancer metastasis." (PMID 38296970, 2024). "To decipher the mechanisms by which SMYD2 regulates breast cancer metastasis, we systematically identified potential SMYD2 methyltransferase substrates through an unbiased proteomic screen." (PMID 38296970, 2024). "In breast cancer, the increase in H3K36me2 by SMYD2 is involved in upregulating the melanoma cell adhesion molecule (MCAM) gene and regulating the characteristics of cancer stem cells." (PMID 39482529, 2024). "Using a genetically engineered mouse model of mammary cancer, we characterize SMYD2 as a critical regulator of metastasis in vivo." (PMID 38296970, 2024). "Next, we sought to verify if SYMD2i can phenocopy our observations in the PyMT mammary cancer mouse model, in which Smyd2 knockout largely blocked metastasis development." (PMID 38296970, 2024). "Overexpression of SMYD2 has been observed in several types of cancer, including breast cancer, lung cancer, and hepatocellular carcinoma." (PMID 37971632, 2023).
breast carcinoma (continued). "In breast cancer, RPL37A expression, in conjunction with metastases suppressor 1 (MTSS1), as well as SET and MYND domain-containing protein 2 (SMYD2), were shown to predict the response of breast cancer patients to neoadjuvant doxorubicin and cyclophosphamide." (PMID 36008952, 2022). "SMYD2 has been demonstrated to play pivotal roles in multiple tumors, such as acute lymphoblastic leukemia, breast cancer, and gastric cancer." (PMID 36611819, 2022). "More relevantly, SMYD2 has been established to coordinate with EZH2 to promote breast cancer tumorigenesis and metastasis." (PMID 34544413, 2021). "Blockade of SMYD2-induced cell cycle arrest at the G1/S phase was observed in breast cancer cells and Pkd1-mutant cystic renal cells." (PMID 34359832, 2021). "Recently, SMYD2 was observed to involve into the upset and progression of various tumors including leukemia, breast cancer, teratocarcinoma, gastric cancer, and head and neck cancer." (PMID 31106145, 2019). "In SMYD2 knockdown breast cancer cells, AKT phosphorylation levels are attenuated, while PTEN phosphorylation at Serine 380 is increased." (PMID 31370883, 2019). "A growing number of studies have revealed the important role of SMYD2 in several types of cancer, including breast cancer, leukemia, esophageal squamous cell carcinoma, and gastric cancer." (PMID 31370883, 2019). "It has been reported that SMYD2 was involved into the upset and progression of various tumors, including leukemia, breast cancer, gastric cancer, and head and neck cancer." (PMID 31106145, 2019). "The genetic alterations of histone methyltransferases, including SMYD2, in breast cancer were systematically investigated in breast cancer samples from the cancer genome atlas (TCGA) database via cBio Portal16,17." (PMID 29487338, 2018). ".In addition, significantly elevated SMYD2 copy number was found in all subtypes of breast cancer and increased SMYD2 levels were correlated with poor patient survival." (PMID 29487338, 2018). "We found that SMYD2 was upregulated in almost all cancer types based on the cross-cancer alteration summary for SMYD2, which included 91 studies, and this was particularly true in breast cancer samples." (PMID 29487338, 2018). "SMYD2 was expressed at significantly higher levels in breast cancer cell lines and in breast tumor tissues." (PMID 29487338, 2018). "For instance, knockdown of SMYD2 inhibited Akt phosphorylation via decreased PTEN methylation that resulted in the growth suppression of breast cancer cells." (PMID 28187429, 2017). "Additionally, our data indicated that SMYD2 inhibitors are well tolerated in pre-clinical animal models and are promising therapeutics to prevent breast cancer metastatic spread, a major unmet clinical need for breast cancer patients." (PMID 38296970, 2024). "Finally, our study provides the rationale for therapeutic targeting of SMYD2 activity to prevent breast cancer cells invasiveness and to impede metastasis." (PMID 38296970, 2024). "Importantly, our in vivo analyses concurred that pharmacological inhibition of SMYD2 enzymatic activity constitutes a clinically targetable vulnerability to prevent breast cancer metastatic burden." (PMID 38296970, 2024). "SMYD2 regulates breast cancer metastasis by controlling cytoskeleton remodeling." (PMID 39482529, 2024). "SMYD2 levels were relatively similar in all breast cancer cell lines tested." (PMID 38296970, 2024). "Notably, in the case of breast carcinoma, the frequency of high-level amplification accounted for 18.6% and 19.2% of the alterations in SMYD2 and SMYD3, respectively." (PMID 38892284, 2024). "SMYD2 and SMYD3 are upregulated in 10% of patients with breast cancer and are significantly associated with cancer progression and poor prognosis in luminal breast cancer." (PMID 35453496, 2022). "In addition to ERα, phosphatase and tensin homolog (PTEN) is also a substrate of SMYD2 in breast cancer cells." (PMID 31370883, 2019).
breast carcinoma (continued). "In triple negative breast cancer, PTPN13, the transcriptional target gene of SMYD2, could be phosphorylated by SMYD2 and link SMYD2 to breast cancer associated signaling pathways, such as ERK, and mTOR signaling pathways, further affected breast cancer growth." (PMID 31548876, 2019). "We should emphasize that SMYD2 was also upregulated in other types of breast cancer." (PMID 29487338, 2018). "In silico analyses and SMYD2 protein expression patterns in ESCC, HCC, and breast cancer primary tumors and/or cell lines suggest that these tumor types may be potentially driven by SMYD2." (PMID 25825497, 2015). "However, as a caveat, a three-dimensional distribution of samples according to expression levels of SMYD2 could predict in vitro responsiveness to doxorubicin in women with breast cancer." (PMID 36838987, 2023). "However, whether the mechanisms identified for SMYD2 in TNBC work in other breast cancer need to be further investigated in the future." (PMID 29487338, 2018). "Thus, targeting SMYD2 may also be a potential therapeutic strategy in other types of breast cancers." (PMID 29487338, 2018). "In addition, we confirmed that PTPN13 is a SMYD2 transcriptional target gene in TNBC cells, which may link SMYD2 to other breast cancer associated signaling pathways, including ERK, mTOR, and Akt signaling." (PMID 29487338, 2018). "Our study links for the first time SMYD2, BCAR3 and FMNL proteins into a common pathway regulating cellular motility and breast cancer neoplastic cells capacity to metastasize." (PMID 38296970, 2024). "Corresponding with elevated BCAR3 and SMYD2 levels, we detected a robust endogenous BCAR3 methylation signal using the specific BCAR3 K334me1 antibody in the metastatic breast cancer lines." (PMID 38296970, 2024). "In comparison with normal individuals, mRNA levels of SMYD2/3/5 are significantly increased and those of SMYD1/4 are reduced in patients of breast cancer." (PMID 36520265, 2022). "Inhibition of either SMYD2 or CDK4/6 would restore the ciliation of cystic renal epithelial cells and breast cancer cells." (PMID 34359832, 2021). "We identified SMYD2, a SMYD (SET and MYND domain) family protein with lysine methyltransferase activity, as a novel breast cancer oncogene." (PMID 29487338, 2018). "Next, we performed quantitative RT-PCR (qRT-PCR) analysis to measure the mRNA expression level of eight HMTs (SETDB1, ASH1L, SMYD2, SMYD3, SETD1A, WHSC1L1, SUV420H1, and SETDB2) in 20 breast cancer cell lines." (PMID 25537518, 2015). "For ASH1L, 11 of 20 cell lines; for SMYD2, 14 of 20; and for SMYD3, 6 of 20 breast cancer cell lines had two-fold higher mRNA levels." (PMID 25537518, 2015). "Among the five most frequently amplified HMT genes (frequency>10%) in breast cancers, four were localized on the long arm of chromosome 1, with SETDB1 at 1q21.3, ASH1L at 1q22, SMYD2 at 1q32.3, and SMYD3 at 1q44." (PMID 25537518, 2015). "For instance, STAG1 is a cell cycle regulator and its overexpression is reported for breast cancer and cellular proliferation, while the methylation of RB1 by SMYD2 enhances cell cycle progression." (PMID 23922792, 2013). "In women with breast cancer submitted to neoadjuvant chemotherapy based in doxorubicin, tumor expression of groups of three genes (PRSS11, MTSS1, CLPTM1 and PRSS11, MTSS1, SMYD2) have classified them as responsive or resistant." (PMID 18601734, 2008). "SMYD2 could methylate PTEN at lysine 313, thereby activating PI3K-AKT pathway and driving the proliferation of breast cancer cells." (PMID 40777131, 2025). "We further validated SMYD2 as the principal enzyme tasked with generating physiologic BCAR3 K334me1, based on both depletion and reconstitution experiments in multiple independent breast cancer cell lines." (PMID 38296970, 2024). "While EZH2 has previously been linked to breast cancer metastasis, the participation of SMYD2 in breast cancer metastasis has been suggested but never demonstrated." (PMID 38296970, 2024).
breast carcinoma (continued). "In addition, SMYD2 expression is higher in aggressive TNBC and Basal-like breast cancers, two subtypes more prone to metastasis development compared to other breast cancers." (PMID 38296970, 2024). "Additionally, SMYD2 can stimulate the phosphorylation of AKT and ERK1/2 by modulating PTPN13 in breast cancer cells." (PMID 39440063, 2024). "While SMYD2 is overexpressed in aggressive breast cancers, we notice that it is not required for primary tumor growth." (PMID 38296970, 2024). "A correlation analysis between the expression of SMYD2 and candidate substrates in metastatic vs non-metastatic breast cancer identified BCAR3 as the strongest positive hit in metastatic breast cancer." (PMID 38296970, 2024). "Other PKMTs like JMJD2C, SMYD2, have also been reported in human cancers such as colorectal cancer, breast cancer, but information on PKMTs are generally lacking in LUAD." (PMID 36604642, 2023). "SMYD2 plays an important role in various cancers; for example, it increases zeste homolog 2 methylation and promotes epithelial-to-mesenchymal transition (EMT) in breast cancer cells." (PMID 36816359, 2023). "In addition, SMYD2 can promote the phosphorylation of AKT and ERK1/2 by regulating PTPN13 in breast cancer cells." (PMID 36611819, 2022). "In the basal-like breast cancer subtype, compared with non-basal subtypes, the expression levels of SMYD2 were significantly higher (p < 0.001)." (PMID 29487338, 2018). "Notably, we found that eight HMTs exhibited high-level amplification in more than 5% of breast cancers, and five of these eight HMTs (SMYD3, SETDB1, ASH1L, WHSC1L1, and SMYD2) had high-level amplification in more than 10% of samples." (PMID 25537518, 2015). "Primary breast cancer tumors were not available, but all breast cancer cell lines tested expressed SMYD2 to a similar degree." (PMID 25825497, 2015). "In a previous study, breast cancer cells were 5 times more sensitive to LLY-507 after seven days of treatment compared to three to four days, indicating that at least some of the SMYD2-dependent epigenetic mechanism may be responsible for the proliferation of breast cancer cells." (PMID 37513898, 2023). "Further bioinformatic analyses showed that SMYD2 expression, but not EZH2, is elevated in breast cancer metastases compared to primary tumors." (PMID 38296970, 2024). "In contrast, MCF7 showed higher expression of SETDB1, but not ASH1L and SMYD2, which is consistent with amplification of SETDB1, but not ASH1L and SMYD2, in this breast cancer cell line." (PMID 25537518, 2015).